EZH2 (enhancer of zeste 2 polycomb repressive complex 2 subunit)
Diseases named in the same sentence as EZH2 in open-access papers (continued):
Sharing a sentence is not in itself a finding about the gene and the disease.
cancer (continued). "There have been several recent clinical trials of EZH2 inhibitors in various cancers being studied." (PMID 36686830, 2022). "Commonly, EZH2 serves actively in stimulating tumorigenesis, and EZH2-mediated H3K27m3 might be involved in cancer progression." (PMID 35414117, 2022). "For example, the overexpression of EZH2 has been detected in prostate, breast, and other cancers, suggesting that it might serve as a prognostic marker for cancers." (PMID 35419278, 2022). "EZH2 inhibits the transcription of target genes by methylating histones, and its abnormal levels have been demonstrated to be correlated with the development of malignant tumours." (PMID 35379783, 2022). "Based on EZH2’s role in cancer progression, such circRNAs can enhance EZH2 expression." (PMID 35236381, 2022). "Currently, the research on epigenetics involving EZH2, DNA methyl transferases (DNMTs), as well as histone methyl transferases (HMTs) has absorbed increasing attention, with their corresponding inhibitors displaying great value in cancer treatment." (PMID 36195655, 2022). "In addition to pre-clinical experiments, clinical studies have also evaluated role of EZH2 inhibitors in treatment of cancer patients." (PMID 35236381, 2022). "The EZH2 signaling affects TME to regulate cancer progression." (PMID 35236381, 2022). "EZH2 is an essential partner of YY1 in promoting cancer cell progression." (PMID 35406384, 2022). "The approval of Tazverick may just be the being as CliniclaTrials.gov listed 51 active trials into EZH2 inhibitors in cancer as of February 2022." (PMID 36359771, 2022). "The EZH2-PPARγ axis has been confirmed to promote cancer proliferation." (PMID 36263120, 2022). "Many studies have verified that EZH2 plays a prometastatic role in various cancer types, and that the pharmacological inhibition of EZH2 can significantly repress the migration and invasion of the cancer cells." (PMID 35429301, 2022). "Aberrant EZH2 expression (usually upregulation) and activity in cancers is a consequence of genetic, transcriptional, post-transcriptional, and post-translational modifications which have been documented in various cancer types." (PMID 36230683, 2022). "Since CTR9 depletion generates therapeutic vulnerability to pharmacological inhibition of PRC2, the CTR9 expression levels may be used as a biomarker for predicting PRC2 dependency and EZH2 inhibitor sensitivity in broad cancer types." (PMID 35137163, 2022). "Some of the lysine and arginine methyltransferases widely studied in anti-cancer therapeutics include G9a, EZH2, DOT1L (disruptor of telomeric silencing 1-like protein) and PRMT1 (protein arginine methyltransferases 1), inhibitors of which are being extensively investigated." (PMID 35438143, 2022). "Clinical trials targeting EZH2 methylase (KMT6A) activity for cancer therapy are ongoing." (PMID 35406676, 2022). "Just like EZH2, NF-κB has long been regarded as a potential therapeutic target of cancer." (PMID 36263173, 2022). "Noteworthy, EZH2 signaling can regulate response of cancer cells to immunotherapy." (PMID 35236381, 2022). "EZH2 upregulation can promote cancer metastasis via EMT induction." (PMID 35236381, 2022). "Moreover, in some cancer types, including THYM, BRCA, HNSC, and KIRC, the immune infiltration degrees were markedly associated with EZH2." (PMID 35659256, 2022). "Then, the expressions of EZH2 and p57 genes in cancer cells were studied." (PMID 35321452, 2022). "Therefore, EZH2 stabilization leads to cancer progression and silencing EZH2 diminishes cancer proliferation and metastasis." (PMID 35236381, 2022). "EZH2 regulates cell cycle progression, and the dysregulation of EZH2 accelerates cell proliferation and prolonged cell survival, which may lead to cancer development." (PMID 35993051, 2022). "Moreover, EZH2 is involved in the regulation of immune cells (e.g., T cells, NK cells, dendritic cells and macrophages), which are essential components in the cancer microenvironment." (PMID 35408658, 2022).
cancer (continued). "For this reason, EZH2 is currently considered a novel and promising target for cancer therapy." (PMID 36362406, 2022). "Furthermore, H1-2 was observed to be overexpressed in cancer cells acting as a silencer of multiple growth suppressors dependent on EZH2-mediated H3K27me3 resulting in modulation of the chromatin architecture." (PMID 33806030, 2021). "Besides, EZH2 protein was found to be over-expressed in drug-resistant cancer cells and a nanoparticle system containing siEZH2 can reverse cisplatin resistance." (PMID 33494783, 2021). "Several methyltransferases such as EZH2, SETD2 and Dot1L have been implicated in cancers." (PMID 34552611, 2021). "It was previously reported that EZH2 and cancer metastasis are relevant." (PMID 33934088, 2021). "Interestingly, NFATc1- and EZH2 co-occupied genes were involved in pathways with critical implications in cancer, such as calcium or Hippo signaling." (PMID 34943970, 2021). "It would be interesting to see in the future whether EZH2 induction plays a critical role in promoting therapy resistance in these E.C.M. detached cancer cells or C.T.C.s." (PMID 33531586, 2021). "Inhibitors of DNA methyltransferases (DNMTi: 5-Aza, decitabine), histone deacetylases (HDACi: Vorinostat, Panobinostat, valproic acid, etc.)and histone methyltransferases (HMTi: EZH2 inhibitors -Tazemetostat) are undergoing clinical trials for cancer treatment with some being already approved." (PMID 33671123, 2021). "EZH2, an important methyltransferase, is considered as a potent therapeutic target in many cancers." (PMID 33868269, 2021). "EZH2, for example, has been associated with metastatic PCa development post-radiotherapy, correlated with genomic drivers of PCa progression such as PTEN, and found to cooperate with BRCA1 to maintain cancer stem cell populations in PCa." (PMID 33525365, 2021). "Interestingly, we found decreased levels of both Suz12 and EZH2 subunits in CD4+ T cells co-cultured with MDA-MB-231 cancer cells." (PMID 34439305, 2021). "Interestingly, it is also reported that EZH2 directly methylates pivotal regulators and thus regulates the progression of several cancers 8,20." (PMID 34335938, 2021). "Enhanced EZH2 expression indicates the poor prognosis of different cancers." (PMID 34335938, 2021). "In light of the prevalent and conserved roles of EZH2, DNMT3a, lncRNAs, and miRNAs in epigenetic regulation, the potential implications of the SChLAP1/EZH2/miRNA axis and the feedback loop between miRNAs and DNMTs in other human cancers also deserve further explorations." (PMID 33589600, 2021). "While many cancer-specific alterations in PcG subunits are related to specific developmental pathways or cancer-specific phenotypes, some sets of paralogs are universally up and downregulated across multiple cancers, including EZH2/EZH1, RING1B/RING1A and (CBX2/CBX8)/(CBX6/CBX7)." (PMID 34617019, 2021). "Next, to evaluate whether OGT regulates the expression of EZH2 to influence live cancer progression, OGT was overexpressed or silenced EZH2 in HCC‐LM3 and Huh‐7 cells as follows, oe‐NC + si‐NC, oe‐OGT + si‐NC, and oe‐OGT + si‐EZH2." (PMID 34510715, 2021). "EZH2 is overexpressed in many cancer types, such as cancer of the endometrium, and prostate gland." (PMID 34776951, 2021). "Enhancer of Zeste Homolog 2 (EZH2) inhibitors (EZH2i) are approved to treat certain cancer types." (PMID 34925340, 2021). "The lncRNA UFC1 has been known as an oncogenic lncRNA regulating EZH2 signaling in cancer." (PMID 34439315, 2021). "We also found a high expression of AMPK and EZH2 in matrix detached cancer cells." (PMID 33531586, 2021). "Thus, EZH2 has been considered a bona fide therapeutic target in cancer therapies, and inhibitors targeting EZH2 have been increasingly developed, such as tazemetostat (EPZ-6438), valemetostat, CPI-0209 and CPI-1205 33-36." (PMID 34512145, 2021).
cancer (continued). "We previously demonstrated that FAK silencing may reduce in vitro and in vivo HCC growth by affecting the expression of cancer-promoting genes, including the pro-oncogenic EZH2." (PMID 34784956, 2021). "For example, the INK4B-ARF-INK4A tumor suppressor gene locus is a well-known target of EZH2 and its inhibition affects cancer growth and embryonic development; E-cadherin gene is another critical target of EZH2, and its down-regulation is essential for EMT and metastasis." (PMID 34938735, 2021). "Many reports have demonstrated that EZH2 is ectopically expressed in cancer cells." (PMID 34775498, 2021). "Therefore, EZH2 has been recognized as a bona fide target in cancer therapies, and many EZH2 inhibitors have been evaluated in clinical trials, such as GSK126 and EPZ005687." (PMID 34065631, 2021). "EZH2 is an epigenetic modifier that is overexpressed in multiple cancer types." (PMID 34503116, 2021). "Reprograming the TIME by targeting EZH2 is a viable area of cancer research." (PMID 33868269, 2021). "Inhibiting EZH2 has potential therapeutic effects on a variety of cancers." (PMID 34335707, 2021). "Here, we investigated strategies to upregulate GD2 also in OS, starting with the hypothesis that epigenetic modification by inhibition of EZH2 could induce GD2 expression also in this cancer." (PMID 33811471, 2021). "Our previous study also summarized the correlation between EZH2 and the key genes involved cellular metabolic pathways to propose a potential strategy that combination of EZH2i with metabolic regulators will be useful for future cancer therapy." (PMID 33761979, 2021). "Dysregulation of EZH2 has been shown to play an oncogenic role in various cancers." (PMID 35178361, 2021). "Mapping genome-wide H3K27 methylation in aggressive cancer tissues and Oncomine-derived microarray data led to the generation of a polycomb repression signature of 14 direct targets of polycomb group proteins such as EZH2." (PMID 33525365, 2021). "The overexpression of EZH2 has been observed in a number of human cancers." (PMID 34298617, 2021). "KONDO_EZH2_TARGETS consists of genes upregulated by EZH2 knockdown in cancer." (PMID 34830428, 2021). "A decreased EZH2 expression can also increase the expression of RKIP in cancer cells." (PMID 34944867, 2021). "Several studies have shown that EZH2 was closely related to the survival of cancer patients." (PMID 34381492, 2021). "Besides the H3K27me3 signatures, the EZH2 ChIP-seq targets were enriched in several cancer-related pathways." (PMID 33713851, 2021). "Thus, understanding the regulation of the abundance and activity of EZH2 is of great importance to not only the delineation of the pathophysiological function of EZH2 but also the prevention and treatment of various cancers." (PMID 33849069, 2021). "Therefore, we summarized and analyzed the potential carcinogenic effect of EZH2 for the first time based on TCGA (cancer genome map) datasets." (PMID 34381492, 2021). "The enzyme has been found to be overexpressed in wide varieties of cancer, such as prostate, liver, gastric, breast, bladder, lung, and pancreatic cancers with literature precedents ascertaining the role of EZH2 in augmenting the development and progression of cancer." (PMID 33840388, 2021). "Prominently, SNHG1 could epigenetically suppress gene expression through recruiting EZH2 in various cancers." (PMID 34806925, 2021). "An outstanding example of such regulator is EZH2 (a histone methyl transferase which is the catalytically active component of the PRC2 complex), which has been found to be mutated or overexpressed in a number of cancers." (PMID 34153035, 2021). "One of the recent papers reported that eudesmin also downregulates EZH2 expression in cancer cells." (PMID 34577136, 2021). "Moreover, the interaction between AFAP1-AS1 and EZH2 and subsequent recruitment of EZH2 to the promoter of p21 has been shown to repress expression of p21 in this type of cancer." (PMID 34912717, 2021).
cancer (continued). "Next, by using apoptosis assay, we found strong induction of apoptosis during EZH2 activity inhibition, suggesting the critical role of the repressive EZH2 methylation in maintaining both proliferation and viability of cancer cells in E.C.M. detached conditions." (PMID 33531586, 2021). "Enhancer of zeste homolog 2 (EZH2), a histone methyltransferase that catalyzes histone H3 lysine 27 trimethylation (H3K27me3) and epigenetically silences target genes, is overexpressed in many cancer types and has been shown to act as an oncogene." (PMID 34778084, 2021). "However, more recent studies have begun to reveal that EZH2 and G9a act cooperatively to mediate gene silencing in both normal and cancer cells." (PMID 33436557, 2021). "Increased EZH2 promotes cancer cell growth and an epithelial-mesenchymal transition." (PMID 34001289, 2021). "Indeed, accumulating studies in various types of cancer have highlighted that inhibition of EZH2 suppresses cancer initiation, progression, and metastases." (PMID 34815475, 2021). "Some reports have suggested that the downregulation of EZH2 level upregulates p21 level in cancer." (PMID 33934088, 2021). "The CPTAC dataset was used to analyze the EZH2 total protein in different malignant tumors of TCGA." (PMID 34381492, 2021). "Besides EZH2, typical epigenetic modification enzymes and cancer-promoting factors, SETDB1, G9A, and SETD1A, were inhibited." (PMID 34595169, 2021). "Moreover, miR-26a, miR-138, and miR-124 also participate in the post-transcriptional regulation of EZH2 in different types of cancer cells." (PMID 34811354, 2021). "Accordingly, inhibition of EZH2 might be a promising strategy for therapies of cancers in the future." (PMID 34551671, 2021). "EZH2 inhibitors have emerged as a promising therapeutic strategy for cancer patients." (PMID 34571873, 2021). "The results showed that gRNAs that target EZH2 were enriched in the surviving cells, which suggested that EZH2 might be involved in the cancer cell response to glucose deprivation." (PMID 34671029, 2021). "PTMs are distinct approaches for the adjusted modification of EZH2 in the development of cancer." (PMID 34745848, 2021). "Given that the imbalance between KDM6A and EZH2 expression appears to sensitize many cancers to epigenetic inhibitors, resetting epigenetic balance could be useful in combination approaches." (PMID 34950587, 2021). "The functions of EZH2 in cancer cells have been extensively studied." (PMID 34737746, 2021). "However, EZH2 inhibitors cannot completely inhibit the oncogenic activity of EZH2 in SWI/SNF mutant cancers." (PMID 34288823, 2021). "Importantly, SNHG6 has also been identified as a molecular sponge of miR-101, -214 and -4465, which all target EZH2 in different cancers 154-156." (PMID 34512145, 2021). "For these cancers, chemical approaches to degrade EZH2 are being explored." (PMID 34617019, 2021). "We next exposed PAH-PASMCs to escalating doses of EPZ-6438 (Tazemetostat) and GSK-126 for 48 h; two selective S-adenosyl methionine competitive inhibitors of histone methyl transferase EZH2 currently being evaluated in clinical trials for the treatment of cancer." (PMID 33803922, 2021). "Some of these EZH2 inhibitors are in clinical trial in patients with cancer." (PMID 34968294, 2021). "In addition to focusing on the role and application of EZH2 in cancer cells, studies have also paid attention to the role of EZH2 in the development and function of the immune system." (PMID 34737746, 2021). "The elevated expression of EZH2 often correlates with a poor prognosis in cancer patients." (PMID 33849069, 2021). "Therefore, the overall effect of Ezh2 inhibition on cancer cell/T cell interaction is the result from summation of Ezh2 inhibition on Treg and CD8+ T cell function." (PMID 33403469, 2021). "The association of EZH2 with aggressive morphologic variants in other types of cancer has been reported, but not in MCL previously." (PMID 34376807, 2021).
cancer (continued). "Thus, CARM1 promotes cancer by both directly enhancing the activation of the IRE1α/XBP1s pathway and indirectly mediating the silencing of EZH2 target genes." (PMID 34493732, 2021). "Upregulation of the H3K27me3 methyl-transferase EZH2 has been observed in various cancers." (PMID 33966039, 2021). "For EZH2 is over-expressed in various cancers, inhibitors against EZH2 have also been developed." (PMID 34288823, 2021). "However, the impairmentof EZH2 activity by orthosteric intervention has proven to be effectiveonly in a limited subset of cancers." (PMID 34351144, 2021). "Since inhibition of EZH2 was reducing the cell proliferation, we were interested in finding out whether clustering was important for high EZH2 expression in E.C.M. detached cancer cells." (PMID 33531586, 2021). "In addition, several clinical trials concerning EZH2 inhibitor therapy for different types of malignant tumors are ongoing (ClinicalTrials.gov: NCT02601950, NCT01897571 and NCT04407741)." (PMID 35186711, 2021). "In cancers and infections that have worst outcomes in males versus females, one approach might be to target (inhibit) the EZH2 epigenetic regulator that opposes KDM6A." (PMID 33469152, 2021). "Activities of the lncRNA ANCR in binding EZH2 and promoting its phosphorylation have been reported by several research groups, but the overall effects of this regulation on cancer cells varied, likely depending on cancer types and genetic backgrounds." (PMID 34512145, 2021). "Hence, many researchers have tried to discover potent inhibitors of EZH2 which can be used as anti-cancer agents." (PMID 34577136, 2021). "The HOTAIR-sbid could inhibit malignant phenotypes of cancer cells through competitively binding with Snail and enhancing the EZH2-mediated repression on Snail epithelial target genes." (PMID 34244473, 2021). "Finally, we generated a Python application to analyze the correlation of EZH2/SUZ12/EED gene knockouts by CRISPR with the alterations detected in the cancer cell lines using DepMap data." (PMID 34202528, 2021). "Results clearly supported our hypothesis, and we found synergy between the AMPK and EZH2 inhibitor in reducing the cell viability of E.C.M. detached cancer cells." (PMID 33531586, 2021). "Over-expression of EZH2 is frequently observed in many cancer types." (PMID 32093341, 2020). "We also explored the clinical significance of EZH2 in cancer." (PMID 33121524, 2020). "Recent evidence suggests that EZH2 plays a role in silencing TEs in cancer cells." (PMID 34968293, 2020). "Therefore, the up‐regulation of EZH2 can promote the metastasis of cancers and play a pivotal role in the progression of cancers." (PMID 32725802, 2020). "EZH2 was intimately involved in platinum resistance according to previous studies: EZH2 was overexpressed in cancer stem-like cells enriched by platinum; EZH2-H3K27Me3 axis induced chromatin condensation, SLFN11 gene silencing, DNA-damage repair deficiency and acquired platinum resistance." (PMID 32435534, 2020). "Previous studies have clarified that miR‐101‐3p regulates various pivotal oncogenes and that downregulation of this miRNA affects cancer cell proliferation, metastasis, drug resistance, and angiogenesis via targeting of several oncogenic targets, e.g. EZH2, STMN1, VHL, SOX2, and DNMT3A." (PMID 31755218, 2020). "Collectively, with what was indicated in the migration and invasion in cancer Section 2.2, it can be seen that the dynamic regulation of EZH2 by various lncRNAs might be one of the key regulations in cancer apoptosis and progression." (PMID 33050646, 2020). "Altered expression of EZH2 has been reported invarious cancers." (PMID 31606963, 2020). "Cancer types with alteration at EZH2 in at least 2% of cases are shown." (PMID 33003334, 2020).